BCL2 (BCL2 apoptosis regulator)
Diseases named in the same sentence as BCL2 in open-access papers (continued):
Sharing a sentence is not in itself a finding about the gene and the disease.
cancer (continued). "ABT‐263 (Navitoclax) is a BH3 mimetic drug targeting anti‐apoptotic B‐cell lymphoma‐2 (BCL‐2) family proteins, with potential anticancer activity against various types of cancer." (PMID 38037859, 2024). "The seeds of Vitis vinifera are particularly rich in proanthocyanidins that can reduce the levels of Bcl-2 in cancer cells in vitro." (PMID 38398737, 2024). "These BH3 mimetics effectively exploit the Bcl-2 interaction network to push cancer cells into apoptosis." (PMID 39048751, 2024). "Because of its extensive effects on immune cells and regulation of programmed cell death, BCL-2 has become an attractive drug target for cancer therapy." (PMID 38062129, 2024). "After infection, we quantified changes in the cellular cancer phenotypes, the gene expression levels of some cancer markers, including Ki-67, BCL-2, VIM, MMP9, and VEGF, and proinflammatory cytokines." (PMID 39427065, 2024). "In HepG2, quercetin helps regulate Bcl-2 and also increases the proportion of cells in the G0/G1 phase, and inhibits cancer cell survival through the regulation of surviving and Bcl-2." (PMID 39062777, 2024). "The relationship between Bcl-2 and Notch proteins plays a significant role in cellular survival mechanisms and therapeutic resistance in various cancer types." (PMID 39684550, 2024). "The regulation of these pathways is an important therapeutic technique in cancer treatment since many cancer cells are resistant to apoptosis due to overexpression of anti-apoptotic proteins such as Bcl-2." (PMID 39770489, 2024). "Compounds were shortlisted on the basis of their ability to inhibit viability of Bcl-2–expressing cancer cells, compared with their control cells." (PMID 38329389, 2024). "Enones-induced apoptosis in cancer cells was characterized by downregulation of antiapoptotic Bcl-2 and overexpression of pro-apoptotic Bax." (PMID 39463485, 2024). "Overall, the modulation of the BCL2 protein expression downstream to the ionic perturbation emerges as a crucial determinant for the anti-cancer effects of CGs as a single agent and even more in combination with BCL2 inhibitors." (PMID 37904054, 2024). "The BCL-2 gene is known for its anti-apoptotic properties, and its expression levels can provide insight into the apoptotic response of cancer cells to treatment." (PMID 39176367, 2024). "Dysregulation of Bcl-2 expression can lead to prolonged cell survival, thereby contributing to conditions such as cancer." (PMID 38786985, 2024). "MiRNA-30a is also closely related to apoptosis in cancer cells, promoting apoptosis through the expression of down-regulated BCL-2 expression." (PMID 38200421, 2024). "Dysregulation of BCL-2 and related antiapoptotic proteins often contributes to chemotherapy resistance, making them potential targets for cancer therapy." (PMID 39193333, 2024). "During tumor progression, cancer cells often down-regulate pro-apoptotic proteins, such as Bax while up-regulating anti-apoptotic proteins like Bcl-2 and Bcl-XL, thereby protecting themselves from apoptosis." (PMID 39598398, 2024). "Bcl-2 inhibitors have gained significant attention in cancer therapy due to their ability to promote apoptosis in cancer cells by neutralizing the anti-apoptotic functions of the Bcl-2 family proteins." (PMID 39407697, 2024). "The ability to target and kill Bcl-2–expressing cells is exceptionally promising, as Bcl-2 is overexpressed in several cancers including TNBC." (PMID 38329389, 2024). "B-cell lymphoma/leukaemia-2 (Bcl-2) proteins, instrumental in the intrinsic apoptotic pathway, occupy a pivotal role in maintaining the delicate equilibrium between cancer cell survival and apoptosis." (PMID 38503887, 2024).
cancer (continued). "Resveratrol, especially when combined with temozolomide, significantly inhibits STAT3 activation, reducing the expression of downstream effectors like Bcl-2 and survivin, which normally help cancer cells evade death." (PMID 39769099, 2024). "A number of small molecule antagonists, termed “BH3-mimetics”, have been developed to target anti-apoptotic Bcl-2 proteins in cancer." (PMID 38542429, 2024). "HFF stably expressing GFP protein, exposed to CM from Bcl-2 overexpressing M14 cells, also expressed higher levels of α-smooth muscle actin (α-SMA), an established cancer associated fibroblasts (CAFs) marker, and ERK1/2 phosphorylation." (PMID 38755629, 2024). "Selective targeting of Bcl-2 and elimination of cancer cells expressing Bcl-2 opens up new therapeutic avenues." (PMID 38329389, 2024). "Bcl-2 and Bcl-xL are believed to play roles in the pathogenesis of cancer and also resistance to therapeutics." (PMID 39272802, 2024). "Concurrently, CSPG4P12 overexpression results in a significant reduction in the levels of Bcl-2, an anti-apoptotic protein that typically contributes to cell survival and resistance to cell death mechanisms in cancer cells." (PMID 38877481, 2024). "Accordingly, BH3 mimetics designed to block the sequestration capacity of anti-apoptotic BCL-2 proteins towards BH3-containing pro-apoptotic interactors sensitize cancer cells to NK- and T-cell-mediated killing." (PMID 39349429, 2024). "As BCL-2 functions not only in apoptosis but also in cancer cell metastasis as an oncogene, the impact of the drug on cancer cell migration and invasion was investigated." (PMID 38685028, 2024). "Activation of the TLR4/NF-κB pathway promotes cancer cell survival and also increases the expression of anti-apoptosis proteins, such as Bcl-2, which results in reduced efficacy of chemotherapy." (PMID 39451226, 2024). "Since the anti-apoptotic proteins HK-I, HK-II, Bcl-2, and Bcl-xL have been found to be expressed at high levels in many types of cancer, interfering with their interaction with VDAC1 is an appropriate target for inducing apoptosis." (PMID 39334905, 2024). "The identification of BCL-2 as a key driver of cancer pathogenesis has paved the way for the development of BCL-2 inhibitors." (PMID 39594670, 2024). "Inhibitors that mirror the structural domain 3 (BH3) of Bcl-2 can activate apoptosis in cancer cells, making them a promising target for anticancer treatment." (PMID 39517292, 2024). "Although the PERK pathway activates pro-apoptotic factors like DNA damage inducible transcript 3 (DDIT3) and B-cell lymphoma-2 (Bcl-2) family proteins, recent reports suggest that in cancer cells the balance is shifted toward pro-survival signaling." (PMID 38672243, 2024). "For example, nanoparticles conjugated with siRNA targeting the oncogene Bcl-2 have been shown to selectively inhibit the growth of cancer cells overexpressing Bcl-2, resulting in improved cancer treatment efficacy." (PMID 39439717, 2024). "Venetoclax, a BH3 mimetic, binds to Bcl-2, releasing Bcl-2 blocked pro-apoptotic proteins and inducing apoptosis in cancer cells." (PMID 38227162, 2024). "Overexpression of Bcl-2, Bcl-xl, cIAP, and survivin is common in many cancers, which allows cells to evade the intrinsic apoptosis pathway." (PMID 39273231, 2024). "It has been proposed that higher concentration of Achillea extracts can induce apoptotic cell death in different cancer cell lines through upregulating the expression level of Bax and caspase-3 genes and downregulating Bcl-2 expression." (PMID 38218845, 2024). "Bcl-2 antiapoptotic molecules (bcl-2, bcl-xL, and mcl-1) are frequently upregulated in acquired chemo-resistant cancer cells, which block drug-induced apoptosis." (PMID 38673964, 2024). "There is insufficient research on the PTGS2, CASP3, ESR1, and BCL2 targets in cancer-induced fatigue." (PMID 39564104, 2024).
cancer (continued). "We have previously reported that FASN inhibition can result in increased mitochondrial apoptosis priming, placing cancer cells in a primed-for-death state that is “addicted” to BCL-2 anti-apoptotic proteins." (PMID 39349429, 2024). "Mutations in BCL2 and other apoptosis regulators have been reported in VEN-resistance in other cancers." (PMID 38961053, 2024). "Flavonoids are capable of detecting and destroying genetically mutated cells, decreasing the expression of antiapoptotic proteins like Bcl-2, and increasing pro-apoptotic proteins such as Bax, caspase 3, and procaspase 9 in cancer cells." (PMID 39519572, 2024). "Given that Survivin and Bcl‐2 constitute two pivotal pro‐survival mechanisms fostering therapeutic resistance in cancer cells, our revelation that 2,4‐DTBP concurrently downregulates both proteins becomes particularly consequential." (PMID 38494866, 2024). "In this study, an immunostimulatory siRNA with specific overhanging sequence motifs was developed to target the highly expressed classical gene BCL-2 in cancer cells." (PMID 38685028, 2024). "On the other hand, the gene expression of Bcl-2 was significantly decreased in vanillic acid nanocomposite-treated A540 cells compared to that in control cancer cells." (PMID 38999050, 2024). "Fucoidan is able to regulate the mechanism of apoptosis in cancer cells by downregulating the Bcl-2 protein and upregulating Bax, increasing the permeability of the mitochondrial membrane and releasing cytochrome c." (PMID 39407623, 2024). "The aim of the present study was to evaluate the expression of pro‐apoptotic Bax, caspase‐3, and caspase −9, and anti‐apoptotic Bcl‐2 in cancer cells in order to understand the apoptotic pathway induced by GKN1." (PMID 39524138, 2024). "Taken together, these findings indicate that BFC1108 likely interacts with the Bcl-2 loop domain, inducing a Bcl-2 conformation change and promoting cell death in Bcl-2–expressing cancer cells." (PMID 38329389, 2024). "Antiapoptotic B cell lymphoma-2 (BCL-2) family proteins play crucial roles in regulating the apoptotic process, contributing to the survival of cancer cells and enhancing tumor cell viability." (PMID 38927948, 2024). "The interplay between BCL-2 signaling and other abnormal metabolic and growth pathways is well-documented in cancer biology." (PMID 39594670, 2024). "With DT2216 already under clinical trial as the only PROTAC degrader for BCL-xL, our work here lays the foundation for advancing WH244 as a viable candidate for a BCL-xL/BCL-2 dual degrader for use as a cancer therapeutic." (PMID 38548768, 2024). "In vitro wound healing assays and co-cultures were used to evaluate cancer-specific Bcl-2 ability to activate fibroblasts." (PMID 38755629, 2024). "It contains a nucleolin-targeting As1411 sequenceas the backbone, which is appended with a short sequence for partialhybridization with the antisense ON 4625, which can inhibit the antiapoptoticfunction of Bcl-2 and Bcl-xL inducing apoptosis in cancer cells." (PMID 39416965, 2024). "Myeloid cell leukemia-1 (MCL1) is an anti-apoptotic member of the B-cell lymphoma 2 (BCL-2) family and plays a key role in cancer cell survival and resistance to therapy." (PMID 39802137, 2024). "The BH3 domain in Bid and the anti-apoptotic mitochondrial proteins (Bcl-2, Bcl-XL, mitochondrial ATR) it associates with at the outer mitochondrial membrane provides us with a viable target in cancer therapy." (PMID 38927905, 2024). "In cancers such as breast, lung, and lymphoid malignancies, BCL-2 has demonstrated significant prognostic implications." (PMID 39685591, 2024). "Bcl-2 and Bax proteins, as important prognostic biomarkers for cancer, function as a ‘molecular switch' that initiates apoptosis." (PMID 39544485, 2024).
cancer (continued). "Small molecule inhibitors targeting Bcl‐2 have demonstrated superior efficacy across various cancer types." (PMID 39619229, 2024). "The sustained high expression of Bcl-2 confers resistance to antitumor treatments, as these primarily act by inducing apoptosis as a mechanism to eliminate cancer cells." (PMID 39684550, 2024). "In vitro studies have explored the formation of intramolecular G4s in various human gene promoter regions, including those of the c-myc, c-kit, and bcl-2 genes, which play significant roles in cancer development." (PMID 39770021, 2024). "Of these genes, BCL2 is best known as a key cancer target involved in the regulation of caspases and other cell viability mechanisms." (PMID 38195591, 2024). "When the body contains elevated levels of anti-apoptotic proteins such as B cell lymphoma-2 (Bcl-2) and decreased levels of pro-apoptotic proteins like Bcl2-associated X protein (BAX), cancer cells exhibit anti-apoptotic activity, and malignancy increases." (PMID 38915462, 2024). "Genetic variations and dysregulation of Bcl-2 are particularly significant in cancer, as they disrupt the normal apoptotic machinery, enabling cancer cells to evade programmed cell death." (PMID 39840282, 2024). "A structure-based computational study against the HeLa cancer cell related protein targets (BCL-2 (4MAN), AKT-1 (4GV1), MCL-1 (5FDO), and BRAF (5VAM)) was used to determine the most potent biomarker." (PMID 40190673, 2024). "Cancer cells exploit the expression of anti-apoptotic protein Bcl-2 to evade apoptosis and develop resistance to therapeutics." (PMID 38329389, 2024). "Their modulation through the activation of proapoptotic proteins such as Bax and the inhibition of antiapoptotic proteins such as Bcl-2 enhances the therapeutic efficacy against cancer cells." (PMID 38473345, 2024). "Antiapoptotic protein BCL2 is highly upregulated in many cancers compared with normal cells, making it an ideal target for cancer therapy." (PMID 38928195, 2024). "Such inhibition eliminates NF-κB from entering the nucleus and inhibits the expression of anti-apoptotic genes namely Bcl-2 and survivin leading to apoptosis in cancer cells." (PMID 39467702, 2024). "miRNAs inhibited genes associated with cancer development or led to the apoptosis of cancer cells; for example, the VV delivered miR-34a, which repressed the anti-apoptotic protein Bcl-2 and promoted the release of cytochrome c in myeloma cells." (PMID 39204331, 2024). "Since enones increased the proportion of cancer cells undergoing early apoptosis, we investigated how they affected the expression levels of important regulatory apoptotic proteins: Bax, Bcl-2, and executioner caspase-3." (PMID 39463485, 2024). "The inhibition of cell apoptosis by the upregulated antiapoptotic protein Bcl-2 confers a survival advantage, and its inhibition has been known to be involved in chemotherapeutic resistance in various types of cancers." (PMID 38758826, 2024). "Previous studies have shown that ERB-041 and genistein increase the Bax/Bcl-2 ratio and expression of cleaved caspase-3, a marker of apoptosis induction in various human cancers." (PMID 38473712, 2024).
cancer (continued). "The selective BCL2 inhibitor venetoclax is a promising therapeutic strategy for cancers; however, its clinical efficacy in DLBCL is far from satisfactory." (PMID 38918775, 2024). "In the present study, we explored the efficiency of the PA-modified nanoparticles to co-deliver and protect miR-15a and miR16-1 from RNase digestion, restore the correct expression levels of Bcl-2, and induce cancer cell death." (PMID 38543296, 2024). "Many studies have shown that beta-eudesmol triggers caspase 3/7, increases Bax levels, and decreases Bcl-2 levels, leading to cytotoxicity and death in different types of cancer cells." (PMID 39101096, 2024). "Combining BCL-2 inhibitors with CAR-T cells is crucial for enhancing therapeutic efficacy against malignant tumors, warranting further exploration of their mechanisms of action." (PMID 39026380, 2024). "In cancer cells, YY1’s impact extends to the regulation of key anti-apoptotic genes, including Bcl-2, Bcl-xl, Mcl-1, and survivin, known for their involvement in therapeutic resistance and cancer progression." (PMID 38893192, 2024). "Remarkably, BAX/BCL–2 ratio has been widely accepted as a protein expression pattern to estimate the eventual outcome of apoptosis expression in cancer patients." (PMID 38499634, 2024). "Both LXR-623 and GW3965 were reported to have synergistic effects towards BH3 mimetics by downregulating the Bcl-2 expression levels in various cancers such as breast, colon, lung, and glioblastoma confirmed in both in vitro and in vivo studies." (PMID 38550382, 2024). "To study if the subcellular localization of the BCL2 FL protein became affected by TMD mutations, we introduced them into a GFP-BCL2 FL fusion expression construct and transfected them into HeLa cancer cells." (PMID 38670940, 2024). "Cancer cells often upregulate anti-apoptotic proteins such as Bcl-2 and Bcl-XL, while downregulating pro-apoptotic proteins like Bax and Bak." (PMID 39060849, 2024). "Normally, Bcl-2 protein expression is observed to be higher in cancer cells compared to that of normal cells." (PMID 39372197, 2024). "Induced myeloid leukemia cell differentiation protein (MCL1) is a crucial member of the B-cell lymphoma-2 (BCL2) family of apoptosis regulators, playing a significant role in maintaining cellular homeostasis and promoting cancer cell survival." (PMID 38371625, 2024). "Therapeutic activation of apoptosis in cancer cells using the BCL-2 inhibitor (BCL2i) venetoclax has shown remarkable efficacy in clinical trials, both as monotherapy and combination regimens." (PMID 39594670, 2024). "The first generation of senolytics was developed from agents to treat cancer and targeted cell survival pathways, such as proteins from the B-cell lymphoma family 2 (BCL-2) and tyrosine kinases." (PMID 38256903, 2024). "Selective targeting of Bcl-2 through an unexplored region and elimination of cancer cells expressing Bcl-2 open up new therapeutic possibilities." (PMID 38329389, 2024). "The roles of BAX and Bcl-2 in cancer progression have been well documented, demonstrating their importance in apoptosis." (PMID 38473728, 2024).